FURIN (furin, paired basic amino acid cleaving enzyme)
Diseases named in the same sentence as FURIN in open-access papers (continued):
Sharing a sentence is not in itself a finding about the gene and the disease.
cancer (35 papers, 2013 to 2026). A tumor composed of atypical neoplastic, often pleomorphic cells that invade other tissues. "Together, these results show upregulation of FURIN with respect to the other PC genes in cancer, with the resultant loss of the PC gene expression pattern observed in normal cells." (PMID 39859176, 2025). "The pro-protein convertase FURIN (PCSK3) is implicated in a wide range of normal and pathological biological processes such as infectious diseases, cancer and cardiovascular diseases." (PMID 38607027, 2024). "The widespread expression of FURIN and its role in promoting cancer-associated processes such as cell proliferation, migration, and invasion are consistent with the effects of chronic inflammation and oxidative stress observed in COVID-19 patients." (PMID 39350850, 2024). "This study results showed that FURIN was aberrantly expressed in 24 cancers and enormously associated with MMR, MSI, DNA methylation, and TMB." (PMID 33968987, 2021). "In addition, FURIN expression was strongly associated with the expression of ICIs in various cancers, particularly in LGG, GBM, and THYM." (PMID 33968987, 2021). "In addition, FURIN expression also showed strong association between expression levels and immune checkpoint markers in three cancers." (PMID 33968987, 2021). "Besides, FURIN expression was closely associated with the levels of immune infiltration and ICIs in human pan-cancer, specifically in LGG, GBM, and THYM." (PMID 33968987, 2021). "For example, FURIN processes the beta-secretase enzyme in Alzheimer's disease, SNPs in the Furin gene are associated with blood pressure levels, and elevated FURIN expression promotes metastatic activity in various cancer types, and the protein is found in advanced atherosclerotic plaques." (PMID 27527873, 2016). "Overall, these two approaches agreed that besides changes to FURIN expression, the combined change to all PC gene expression and the resultant loss of the normal PC gene expression pattern is what seems to characterize the PC dysregulation in the cancer phenotype." (PMID 39859176, 2025). "Altogether these findings shed light on a two‐step activation of ANGPTL4 by HIF2A and FURIN in senescent cells and its upstream role in promoting the proinflammatory SASP, cancer and potentially other senescence‐associated diseases." (PMID 41347893, 2026). "Evidence of their dysregulation in cancer cells, particularly the overexpression of FURIN, is well documented, leading to proposals for anticancer therapeutic strategies targeting this enzyme." (PMID 39859176, 2025). "A major result concluded that FURIN expression in cancer samples dramatically increased compared to the normal tissues." (PMID 39859176, 2025). "This pattern of dysregulation was distinct from the broader trends observed in a variety of cancer types through bioinformatic analysis of publicly available transcriptomic datasets, where FURIN expression was predominantly upregulated compared to other PCs." (PMID 39859176, 2025). "The relative expression of PC genes seems most relevant, as suggested by the opposite role observed between FURIN and other PCs in some cancer phenotypes." (PMID 39859176, 2025). "The analysis of large publicly available transcriptomic datasets revealed marked differences in PC gene expression patterns between normal and cancer tissues, with FURIN expression significantly elevated in cancer tissues." (PMID 39859176, 2025). "Further bioinformatics analysis correlated changes in FURIN expression with the regulation of genes associated with HPV infection and various cancer types." (PMID 39859176, 2025). "While FURIN is consistently overexpressed in most cancer types, our study with epithelial cells showed the opposite pattern, in which FURIN was consistently downregulated." (PMID 39859176, 2025). "In the three carcinoma derived cells, PC gene expression was affected to a larger extent compared to the neoplasia cells, with FURIN being mostly downregulated." (PMID 39859176, 2025).
cancer (continued). "FURIN, a calcium-dependent protease expressed throughout the body in all vertebrates and many invertebrates, has also been shown to be expressed in cancer cells." (PMID 39350850, 2024). "Integrating these findings with the hypothetical roles of ACE2, TMPRSS2, and FURIN in cancer development provides a more comprehensive understanding of the potential mechanisms at play." (PMID 39350850, 2024). "Inhibition of PCSK9 activity with therapeutic antibodies or small interfering RNAs is used in the clinic to lower blood cholesterol, and RNA interference -based silencing of FURIN (PCSK3) is being evaluated in clinical trials as a cancer treatment." (PMID 39430302, 2024). "In particular, viral proteins such as ACE2, FURIN, and TMPRSS2 are highly likely to be associated with cancer progression." (PMID 39350850, 2024). "In various types of cancer, FURIN activity has been reported to promote many cancer-related processes such as cell proliferation, migration and invasion, or vascularization." (PMID 39350850, 2024). "FURIN, a potential oncogene can target several oncogenic pathways simultaneously, which would be beneficial in improving the efficiency of cancer treatments." (PMID 36299526, 2022). "Further analysis of the expression of CTSL mutant showed a correlation with FURIN and TMPRSS2, suggesting a potential role of CTSL mutations in modulating SARS-CoV-2 entry in cancers." (PMID 35414771, 2022). "FURIN expression was significantly related to the DSS of patients in five cancers (GBM, KIRP, LGG, LUAD, and STAD)." (PMID 33968987, 2021). "In the present study, we systematically investigated 33 types of cancer to find out the correlation of FURIN expression with the prognosis of patients." (PMID 33968987, 2021). "Second, this study mainly focused on using bioinformatic tools to analyze FURIN expression and prognosis in human pan-cancer." (PMID 33968987, 2021). "FURIN level is elevated in various tumor cell lines and primary tumors, and FURIN activity promotes many cancer-related processes, such as cell proliferation, migration or vascularization, for example." (PMID 33679774, 2021). "The Kaplan–Meier method revealed that FURIN expression correlated with DFI in two types of cancers, namely BRCA and STAD." (PMID 33968987, 2021). "We then integrated ImmuneScore and StromalScore to further evaluate the relationship between FURIN expression and immune infiltration across cancers." (PMID 33968987, 2021). "To conclude, the present study has revealed that FURIN is correlated with the prognosis of patients and immune infiltration across cancers, specifically in GBM, LGG, and LUAD." (PMID 33968987, 2021). "FURIN can serve as a significant prognostic biomarker and correlate with tumor immunity in human pan-cancer." (PMID 33968987, 2021). "This study results indicated that FURIN expression was strongly related to ImmuneScore and StromalScore in 10 types of cancers, respectively." (PMID 33968987, 2021). "Since the data of TCGA normal samples are far less than that of tumor samples in some types of cancer, we integrated the data of the TCGA database and the GTEx database to evaluate the differences in FURIN expression in different cancers." (PMID 33968987, 2021). "Previous studies have revealed that furin can serve as an important factor in some types of cancer, which suggests that FURIN can be expressed in immune cells and cancer cells." (PMID 33968987, 2021). "Compared with previous studies, this study is the first to display the irregular expression landscape of FURIN and analyze the correlation of FURIN expression with the prognosis of patients across cancers." (PMID 33968987, 2021). "FURIN has also been found to exhibit anti-cancer properties, some of which have been related to adaptive immunity in various cancers." (PMID 34356057, 2021).
cancer (continued). "Despite exhibiting different roles in different cancer models, FURIN has been suggested as a potential therapeutic target for selective inhibition in different cancers and infectious diseases that exploit the cleavage protease." (PMID 34356057, 2021). "Among them, FURIN correlates with many cancer-related processes such as cell proliferation, migration, invasion, and angiogenesis, which promotes tumor progression." (PMID 32143735, 2020). "The low FURIN expression status in the HPV-positive cancer indicates that the other PCs may be involved in sustaining this cancer phenotype." (PMID 39859176, 2025). "Similarly, other PCs have shown roles in cancer that sometimes oppose FURIN’s function within the same cancer type." (PMID 39859176, 2025). "FURIN was also the predominant PC expressed in cancer cell lines." (PMID 39859176, 2025). "Interestingly, most tumor types exhibited weaker ACE2/TMPRSS2 and ACE2/CTSB correlations compared to normal tissue, whereas the ACE2/CTSL and ACE2/FURIN correlations in normal tissue are weaker than that of most cancer types." (PMID 33707526, 2021). "Also, FURIN expression was related to immune cell infiltration in 6 cancers and ImmuneScore/StromalScore in 10 cancers, respectively." (PMID 33968987, 2021). "Thus, we evaluated the relationship between FURIN expression and levels of immune infiltration across cancers." (PMID 33968987, 2021). "Furthermore, this study totally explored immune checkpoints and 6 tumor-infiltrating immune cells in the TME of 33 cancers to find the correlation of FURIN expression with them." (PMID 33968987, 2021). "FURIN has recently emerged as a potential target in infectious diseases and cancer." (PMID 33679774, 2021). "In this study, we have displayed the expression landscape of FURIN in human pan-cancer, indicated for the first time that FURIN may serve as an important predictive factor in tumor immunity, and revealed the associations between furin and immune therapy." (PMID 33968987, 2021). "In the present study, we completely evaluated FURIN expression across cancers for the first time." (PMID 33968987, 2021). "Furthermore, we found the co-expression of FURIN with 47 immune checkpoint markers across cancers, specifically in LGG, GBM, and THYM." (PMID 33968987, 2021). "The novel results of this study implied that FURIN may recruit and regulate infiltrating immune cells to inhibit or promote the progression of cancers, which strongly reveals that FURIN serves as a key factor in cancer immunity." (PMID 33968987, 2021). "In addition, they implied that FURIN expression was strongly correlated with TMB in 8 cancers and with 4 DNA methyltransferases in 10 cancers." (PMID 33968987, 2021). "Future studies that focus on FURIN expression and tumor immunity in specific cancers may present a more convincing viewpoint according to this issue." (PMID 33968987, 2021). "The precise mechanism of FURIN in these cancers is worth exploring in the future." (PMID 33968987, 2021). "Furthermore, it has been shown that inhibition, knockdown, and genetic ablation of FURIN reduce tumorigenesis in various human cancer cells." (PMID 26137475, 2015). "It has previously been shown that FURIN inhibition reduces tumorigenesis in various human cancer cells, suggesting that Furin inhibition might be a good therapeutic strategy for cancer." (PMID 26167473, 2015). "Thus we then evaluated the correlation of FURIN expression with MSI in human pan-cancer." (PMID 33968987, 2021). "However, FURIN may be overexpressed or underexpressed, depending on the cancer type." (PMID 39859176, 2025). "However, in other cancers, FURIN may act as a tumor suppressor." (PMID 39859176, 2025). "Next, we analyzed the expression values of ADAM17, HSPA5, TMPRSS2, FURIN, and ACE2 in different cancers and corresponding normal individuals." (PMID 35720350, 2022).
cancer (continued). "Other module genes belonged to TGF β signaling (e.g. FURIN and CREB1), a pathway identified already from the pairwise approach and involved in cancer drug resistance." (PMID 36043458, 2022). "ADAM17 mRNA levels were lower than HSPA5 and FURIN but higher than ACE2 and TMPRSS2 in most cancer types." (PMID 35720350, 2022). "According to this study results, we found that FURIN expression was highly related to 5 MMR genes in 14 cancers and to MSI in 11 cancers." (PMID 33968987, 2021). "The common TMPRSS2 and FURIN associated genes CTSL, MYC, AKT1, and SRC displayed positive correlations with their corresponding subjects except for the FURIN and MYC correlation in cancers (R 0.012; p 0.199)." (PMID 33796097, 2021). "Therefore, FURIN may play a key role as a prognostic biomarker across cancer." (PMID 33968987, 2021). "However, the role of FURIN in human pan-cancer is still largely unknown." (PMID 33968987, 2021). "According to this study results, FURIN expression significantly affected the OS of patients in CESC, GBM, LGG, and LUAD across cancers." (PMID 33968987, 2021). "Considering its multiple tumor-promoting effects in various cancers, we focused on TGF-β signaling-related genes, namely TGFBR1, MAP3K8, and FURIN (red arrow)." (PMID 34537073, 2021). "The central association marker, DPP4 positively correlated with ACE2 (normal: R 0.308; cancers: 0.382), TMPRSS2 (normal: R 0.524; cancers: 0.382) and FURIN (normal: R 0.498; cancers: R 0.246) in both datasets." (PMID 33796097, 2021). "FURIN was aberrantly expressed and was strongly correlated with MMR, MSI, TMB, and DNA methylation in multiple types of cancer." (PMID 33968987, 2021). "FURIN had the largest average expression value, but it was not as predominant in the cell lines as with the cancer samples." (PMID 39859176, 2025). "We also focused on the molecular mechanisms by which SARS-CoV-2 may facilitate cancer progression, including the roles of angiotensin-converting enzyme 2 (ACE2), transmembrane serine protease 2 (TMPRSS2), and FURIN." (PMID 39350850, 2024). "The eight cross-cancer CpGs were annotated to genes involved in transport (KCNA3, KCNAB3 and TRAPPC1), signal transduction (AGAP3 and LIME1), microtubule assembly (FES and SHROOM1), and metal binding (FURIN and AGAP3)." (PMID 35710732, 2022). "We report that the mutant CTSL expression correlates with elevated FURIN expression in multiple cancers, while there is no such correlation in a few cancers (FURIN panel); but TMPRSS2 showed either increase or decrease in a few cancers (TMPRSS2 panel)." (PMID 35414771, 2022). "Besides, we analyzed the relationship between FURIN expression and the DSS of patients across cancers." (PMID 33968987, 2021). "However, ACE2/GP2 (R 0.108 in normal and R −0.045 in cancer) and FURIN/GAPDH (R −0.198 in normal and R 0.023) present differential correlations between normal and cancer samples." (PMID 33796097, 2021). "Through surveying CCLE (cancer cell line encyclopedia) expression profiles, we observed remarkably higher mRNA expression levels of both CTSL and FURIN in H2126, potentially indicating TMPRSS2-independent SARS-CoV-2 infection and explaining less efficacy of camostat mesylate in these cells." (PMID 33558541, 2021). "The FURIN is regulated by Smad-dependent canonical TGF-β signaling, and it is a proprotein convertase which plays a role in the cleavage of pro-TGF-β to its mature form, eventually stimulating the positive feedback loop of TGF-β signaling in cancers." (PMID 34537073, 2021). "It is thus not surprising that FURIN inhibitors are suggested in the treatment of various cancers and to prevent infections." (PMID 33679774, 2021). "This study addressed the changes in gene expression of FURIN and the other PCs during HPV-induced malignant transformation of keratinocytes, beginning at the initial stages of oncogenic HPV infections, advancing through epithelial HPV-positive neoplasia cell lines, and culminating in cancer cells." (PMID 39859176, 2025).
cancer (continued). "We found that mRNA expression of HSPA5 was the highest, followed by FURIN and CTSL in the majority of the tumor tissues, and ACE2 expression was the lowest, demonstrating that CTSL might facilitate tumorigenesis and SARS-Cov-2 entry in most cancers." (PMID 35414771, 2022). "Moreover, survival analysis across cancers revealed that FURIN expression was correlated with overall survival (OS) in four cancers, disease-specific survival (DSS) in five cancers, progression-free interval (PFI) in seven cancers, and disease-free interval (DFI) in two cancers." (PMID 33968987, 2021).